TNF (tumor necrosis factor)
Diseases named in the same sentence as TNF in open-access papers (continued):
Sharing a sentence is not in itself a finding about the gene and the disease.
COVID-19 (continued). "COVID-19 patients displayed similar T-cell exhaustion to non-COVID-19 patients, but with a more unbalanced inflammatory/anti-inflammatory cytokine response (IL-6/IL-10 and TNF-α/IL-10 ratios)." (PMID 33272291, 2020). "There is also evidence of elevated TNFα present in blood and diseased tissues of patients with COVID-19, and TNFα levels during time of hospitalization was an independent predictor of patient survival, disease severity, and death." (PMID 33105809, 2020). "Polymorphonuclear (PMN)-MDSC expanded during COVID-19, in particular in patients who required intensive care treatments, and correlated with IL-1β, IL-6, IL-8, and TNF-α plasma levels." (PMID 33110074, 2020). "It has been well demonstrated that COVID-19 patients exhibited elevated inflammatory cytokines such as IL-1β, IL-6 and TNF-α in their serum." (PMID 33172355, 2020). "Trials evaluating the role of TNF blockade in COVID-19 are currently ongoing (ChiCTR2000030089; NCT04425538—evaluating adalimumab and infliximab, respectively)." (PMID 33442386, 2020). "Patients with COVID-19 exhibited hyper-inflammatory signatures across all types of cells among PBMCs, particularly up-regulation of the TNF/IL-1β-driven inflammatory response as compared to severe influenza." (PMID 32651212, 2020). "These authors also found that COVID-19 patients up-regulated IL-1β, antiviral Interferon stimulated genes (ISGs), and genes related to the IL-17, TNF, and NF-κB signaling pathways." (PMID 32612615, 2020). "Previous studies have reported the contribution of TNF-α to the cytokine storm syndrome in more severe cases of COVID-19." (PMID 32707842, 2020). "Intriguingly, severe COVID-19 patients show elevated levels of serum cytokines such as IL-6, TNF-α, and IL-10, and also increased sCD25 in the serum." (PMID 33178221, 2020). "Among these, only TNF has been identified by our analysis as being part of the COVID-19 host target genes." (PMID 33123533, 2020). "The prevalence of the pro- and anti-inflammatory cytokines interleukin receptor-2 (IL-2R), interleukin-6 (IL-6), tumor necrosis factor α (TNF-α) and IL-10 in severe and moderate cases of COVID-19 has also been studied." (PMID 32612515, 2020). "For example, patients with severe COVID-19 had higher levels of IL-6, IL-2R, IL-10, and tumor necrosis factor alpha (TNF-α) than those with moderate disease, the former of which correlated with clinical severity and death." (PMID 33123165, 2020). "Naringenin has been used in experimental models to regulate the production of IL-6 and TNF, cytokines that are increased in COVID-19 and further increased in severe cases." (PMID 33101291, 2020). "Quantitatively, the number of cells producing TNF-α was reduced 3-fold and 2-fold in with COVID-19 compared with CINS and septic patients, respectively (P = 0.009; mean CINS: 272 ± 64; septic: 168 ± 22; COVID-19: 80 ± 14)." (PMID 32687484, 2020). "When we compared the immune responses from patients with mild and severe COVID-19 infections, we found that classical monocytes from severe COVID-19 exhibit IFN-I-driven signatures in addition to TNF/IL-1β-driven inflammation." (PMID 32651212, 2020). "Anti-TNFα therapy has been proposed to be initiated as early as is practicable in hospitalized patients with COVID-19 in order to obtain the possible optimal beneficial effects." (PMID 33519443, 2020). "However, there is evidence that the high viral load in the lungs of COVID-19 patients is associated with an acute inflammatory response comprising epithelial cells and activated macrophages, which are largely responsible for the secretion of the cytokines, such as TNF, IL-6, IL-8, IL-1β, and CXCL10." (PMID 33391014, 2020). "The efficiencies of anti-inflammatory treatments such as glucocorticoids, tocilizumab (TCZ) and anti-TNFα agents in COVID-19 patients were recently investigated by various registered cohort studies." (PMID 32733921, 2020).
COVID-19 (continued). "We found that the CD4+ T cells in the peripheral blood were decreased in individuals infected with COVID-19 but that the levels of TNF-α and IL-6 in the plasma, which can be produced by CD4+ T cells, were significantly increased." (PMID 32976531, 2020). "The TNF-α and IL-6 levels in the peripheral blood of COVID-19 patients in the general, severe and critical groups were significantly higher than those in peripheral blood of the subjects in the normal control group." (PMID 32976531, 2020). "In our study, cytokines including IL-1β, IL-6, IL-10, and TNF-α were elevated in severe COVID-19 and active AOSD, compared with healthy controls, indicating the potential contribution of cytokine storm in pathogenesis of COVID-19 and AOSD." (PMID 33552062, 2020). "Although several key proinflammatory cytokines, including IL-1β, IFN-ɣ, and TNF-α, were modestly increased in COVID-19 patients compared with healthy control participants, the increases were near the lower limit of detection of the assay." (PMID 32687484, 2020). "The rationale of their use is related to the demonstrated presence of TNF in the serum and in some tissues of COVID-19 patients, where it promotes a phlogistic response." (PMID 32521760, 2020). "Excessive accumulation of inflammatory cytokines (IL-1β, TNF, IL-6, etc.), which are produced mainly by monocytes and macrophages, is characteristic of the severe course of COVID-19." (PMID 33329059, 2020). "As for other biological agents, the main safety concerns for TNF inhibitors in the setting of COVID-19 patients is a raise in bacterial and fungal superinfections rates." (PMID 33442386, 2020). "Out of 22 eligible articles that investigated candidate genes (2 as associated with COVID-19), the top-ranked genes in the number of studies were ACE2, CLEC4M (L-SIGN), MBL, MxA (n = 3), ACE, CD209, FCER2, OAS-1, TLR4, TNF-α (n = 2)." (PMID 32917282, 2020). "No significant changes in other cytokines or chemokines measured, including IFN-γ, IL-1β, IL-8 and TNF-α were observed in COVID-19 patients." (PMID 32943497, 2020). "Most patients with COVID-19 exhibit substantially elevated serum levels of pro-inflammatory cytokines, including IL-6, IL-2R, IL-8, IL-10 and TNFα, which is characterized as cytokine storms." (PMID 33365277, 2020). "In the current study, we confirmed the results from previous studies by showing that the TNF/IL-1β inflammatory response is dominant in COVID-19 although a small number of patients were enrolled." (PMID 32651212, 2020). "Higher plasma levels of cytokines, including interleukin (IL)-6, IL-2, IL-7, IL-10, and tumor necrosis factor-α, were found in patients with COVID-19, which implies the occurrence of a cytokine storm and its association with disease severity." (PMID 33335906, 2020). "Serum cytokines including IL-2R, IL-6, IL-8, and TNF-α.were increased significantly with COVID-19 severity." (PMID 32727465, 2020). "Blocks soluble tumor necrosis factor and signal transduction, which helps maintain remission of COVID-19." (PMID 32849654, 2020). "Some of these proinflammatory cytokines, including IL-2, IL-7, IL-10, G-CSF, IP-10, MCP-1, MIP-1a, and TNF-α, are highly elevated in the blood of severely ill COVID-19 patients." (PMID 33101440, 2020). "COVID-19 patients showed that in the peripheral blood inflammatory cytokines such as, IL-2, IL-6, IL-10 and Tumor Necrosis Factor α (TNF-α) increased and CD4+, CD8+, CD16+, CD19+ and CD45+ T cells were decreased, but an increase in Th17 cell proportion." (PMID 32483409, 2020). "All together, these studies underlie the urgent need of clinical trials to obtain additional evidences of the possible efficacy of anti-TNFα treatment on COVID-19." (PMID 33519443, 2020). "A study indicated that COVID-19 patients treated in the intensive care unit with severe clinical features had a high level of innate cytokines IL-2, IL-10, IL-7, TNF-α, chemokines IP-10, MCP-1, and MIP-1A." (PMID 33101440, 2020).
COVID-19 (continued). "Unexpectedly, cluster 4 and 5 exhibited strong associations with IFN-I-responsive genes, in addition to TNF/IL-1β-responsive genes, indicating that severe COVID-19 acquires IFN-I-responsive features in addition to TNF/IL-1β-inflammatory features." (PMID 32651212, 2020). "The “cytokine storm” observed in patients with COVID-19 refers to an early response of pro-inflammatory cytokines, specifically tumor necrosis factor-α (TNF-α), IL-6, and IL-1β." (PMID 32992693, 2020). "A recent paper on COVID-19 positive patients immunological characteristics showed higher levels of TNF-α in severe cases than in moderate cases." (PMID 33424586, 2020). "It was first reported that several pro-inflammatory cytokines and chemokines, including IL-2, IL-7, IL-10, CXCL10 (IP-10), CXCL8, CCL2 (MCP1), TNFα, and IFNγ were higher in the plasma of COVID-19 patients as compared to healthy controls." (PMID 33363221, 2020). "As summarized in, in comparison with six controls, a significantly higher amount of CD4+ T cells from eight COVID-19 patients was able to produce TNF, CD107a, IFN-γ, IL-2, and particularly IL-17 (that showed the highest difference)." (PMID 32632085, 2020). "Here, increases in CRP, IL-6, and TNF-α levels in severe cases compared to mild cases of COVID-19 were revealed." (PMID 33244370, 2020). "In individuals infected with COVID-19, interleukin (IL)−10, 6 and tumour necrosis factor (TNF) -α are increased during the disease." (PMID 32574327, 2020). "Another study including 21 COVID-19 cases reported that severe cases had increased IL-2R, IL-6, IL-10, and TNF-α when compared to moderate cases." (PMID 32727465, 2020). "TNF-α, a new COVID-19 biomarker, has been reported to promote apoptosis of pulmonary epithelial cells and endothelial cells, leading to vascular leakage, alveolar edema, and hypoxia." (PMID 33232275, 2020). "Infliximab and adalimumab that are anti-TNF antibodies are being considered for modulating the hyperinflammation observed in COVID-19 by specifically targeting TNF." (PMID 33708109, 2020). "A retrospective cohort study including 41 COVID-19 patients observed that miR-9 levels were higher in individuals with COVID-19, particularly in non-survivors, and were strongly correlated with increased levels of IL-6, IL-1β, and TNF-α." (PMID 41595522, 2026). "However, it is also important to emphasize that during COVID-19 progression, TNF-α and IFN-γ are the main cytokines involved in inflammatory cell death, impairing vital organs." (PMID 41596343, 2026). "The phenomenon of a cytokine storm – originally characterized in acute severe COVID-19 – refers to an excessive and uncontrolled release of pro-inflammatory cytokines, including interleukin-6 (IL-6), tumor necrosis factor-alpha (TNF-α), and interleukin-1 beta (IL-1β)." (PMID 41497070, 2026). "The increased TNF expression observed in the CC genotype may exacerbate the inflammatory response, worsening COVID-19." (PMID 40506975, 2025). "Specifically, the dysregulation of key cytokines like IL-6, TNF-α, and IL-1β during COVID-19 may directly interfere with thermoregulation, contributing to a diminished febrile response in CAM patients with prior COVID-19 infection." (PMID 40315194, 2025). "The production of IFN-β by perivascular macrophages and damaged endothelial cells in skin lesions of COVID-19 patients were demonstrated, alongside with elevated levels of IL-1, IL-6, and TNF-α, resulting in a disrupted type I IFN and pro-inflammatory cytokine response." (PMID 40649826, 2025). "Two significant cytokines elevated during COVID-19, TNF-α and IL-6, directly affect brain physiology and may drive dysfunctional stress-related responses, mood alternations, and depressive symptoms." (PMID 40918512, 2025). "Accelerated fibrosis: COVID-19-induced alveolar injury and cytokine storms (e.g., IL-6, TNF-α) may synergize with silica/coal dust to accelerate pulmonary fibrosis." (PMID 40337738, 2025).
COVID-19 (continued). "Furthermore, our demonstration that the EAS1-ACE2 axis mediates apoptosis in response to hypoxia and TNFα, key drivers of COVID-19 pathology, provides a mechanistic basis for its contribution to disease severity." (PMID 41093073, 2025). "Therefore, the severity of COVID-19 can be mitigated by NF-κB degradation inhibitors, immunoregulation of NF-κB activation levels, or effective inhibition of TNF-α." (PMID 41282609, 2025). "The serum level of TNF α is elevated and exacerbates inflammatory response in COVID-19." (PMID 40300201, 2025). "The results revealed that polymorphisms in the IL6, IL6R, IL1α, IL1R, IFNγ, TNFα, CRP, VDR, VDBP, and ACE2 genes are the most significant genetic factors influencing COVID-19 prognosis, particularly in terms of the risks of COVID-19 pneumonia, mortality, rehospitalization, and associated mortality." (PMID 40869297, 2025). "Furthermore, it should be noted that patients with MIS-C had significantly higher levels of IL-1β, IL-6, IL-12, and TNF-α compared to patients with COVID-19." (PMID 40066463, 2025). "However, high levels of TNF-α contribute to lung damage and poor outcomes in severe COVID-19 patients." (PMID 40895576, 2025). "Therefore, the primary objective of this study was to comprehensively summarise the available evidence on the potential effectiveness and safety of TNF-α inhibitors in the treatment of moderate-to-critical COVID-19 in inhibitor-naïve patients." (PMID 40481519, 2025). "Taken together, these findings establish that the alterations in PPARG and TNF expression prompted by COVID-19 may also contribute to the decline in cognitive function associated with anxiety." (PMID 40766923, 2025). "COVID-19-related TM may result from a similar process, where molecular mimicry and cytokine-mediated inflammation (particularly elevated IL-6 and TNF-α levels) contribute to spinal cord damage." (PMID 41510433, 2025). "The spike protein has been shown to trigger prolonged expression of cell adhesion markers and the release of various cytokines and chemokines, such as interleukin-6 (IL-6), tumor necrosis factor-alpha (TNF-α), and interleukin-1β (IL-1β), which are commonly observed in severe COVID-19 cases." (PMID 41012643, 2025). "However, TNF-α levels are increased in most COVID-19 patients and are correlated with the severity of the disease." (PMID 40292283, 2025). "In COVID-19, elevated TNF-α and IL-6 levels may suppress albumin synthesis and contribute to hypoalbuminemia." (PMID 40649865, 2025). "Moreover, they exhibited promising anti-inflammatory effects through TNF-α: TNFR2 inhibitory activity in addition to their inhibitory effect on TNF-α and IL-6, the predominant cytokines in COVID-19-related cytokine storm via cell-based anti-inflammatory assay." (PMID 39854441, 2025). "However, the levels of TNF-α and IL-2 were higher in the breastfeeding mothers with COVID-19 than in the vaccinated breastfeeding mothers or in the control group but still within the reference range." (PMID 40141241, 2025). "This assumption could be supported by the observations of increased levels of pro-inflammatory cytokines, mainly IL-6, but also TNF, which although lower when compared to those in adults’ COVID-19, are still elevated above the normal levels." (PMID 39940694, 2025). "Plasmatic TNF/IFN-γ levels in COVID-19 patients could indicate two pathological processes leading to a critical illness." (PMID 39940907, 2025). "The significant reduction in TNF-α levels in the COVID-19 group, particularly at T3, suggests a blunted inflammatory response in these patients, which may impair viral clearance and contribute to infection susceptibility." (PMID 40332340, 2025). "Most cytokines in mixtures with IL-8, TNF-α, MIP-1α, and G-CSF were associated with COVID-19." (PMID 40910046, 2025). "TNF-α, a key pro-inflammatory cytokine, plays a dual role in COVID-19." (PMID 40661964, 2025).
COVID-19 (continued). "TNF and IFN-γ are key proinflammatory cytokines implicated in the pathophysiology of COVID-19." (PMID 39940907, 2025). "Notably, our genetic and epidemiological findings do not negate the work of clinical and mechanistic evidence of elevated proinflammatory cytokines mainly IL 6, IL 1β, and TNF α to COVID-19 severity." (PMID 41359762, 2025). "While Th1 cytokines are vital for an effective antiviral response, excessive release of proinflammatory cytokines, particularly TNF-α and IFN-γ, has been linked to severe COVID-19 symptomatology, including heightened inflammatory response and cytokine storm syndrome." (PMID 40573938, 2025). "—TNF-α and IL-6—play significant roles in several inflammatory diseases including COVID-19." (PMID 40121473, 2025). "Cytokines such as TNF-α and IL-1β are well known for their proinflammatory effects on the endothelium and may play a significant role in vascular dysfunction in COVID-19." (PMID 40495032, 2025). "For instance, genomic and epigenomic profiling of COVID-19 survivors has revealed persistent open chromatin states at IL-1β, TNF, and CXCL10 loci, marked by sustained H3K4me3 and H3K27ac, supporting continued cytokine expression even in the absence of active infection." (PMID 40969755, 2025). "In conclusion, our analysis, conducted in a homogenous and well-matched cohort study, adds to the existing research by confirming the impaired humoral responses to COVID-19 mRNA vaccination in patients with IBD receiving anti-TNF-alpha immunosuppressive therapies." (PMID 40733650, 2025). "Single nucleotide polymorphisms (SNPs) in the TNF-α, IL-6, IL-8, IL-10, CCL5 and CXCL6 genes have been found to be associated with COVID-19 severity, suggesting that SNPs could help explain COVID-19 outcomes." (PMID 40881695, 2025). "The pathologic hyperinflammatory responses in COVID-19 include an uncontrolled release of interleukins (IL), tumor necrosis factor (TNF), C-reactive protein, D-dimer, ferritin, neutrophils and lymphocytes, and other inflammatory modulators, resulting in a systemic cascade of immune dysregulation." (PMID 40481056, 2025). "Previous studies reported increased levels of IL-10, IL-6, and TNF-α in severe COVID-19 patients." (PMID 39856771, 2025). "The top 30 pathways, ranked by adjusted p-value, included the Toll-like receptor signaling pathway, tumor necrosis factor (TNF) signaling pathway, Coronavirus disease-COVID-19, interleukin (IL)-17 signaling pathway, T helper cell (Th17) differentiation, and apoptosis, among others." (PMID 40371107, 2025). "Here we show that human blood monocytes can effectively sense SARS-CoV-2, and subsequently respond by substantial upregulation of the proinflammatory cytokines TNF, IL-1β and IL-6, which comprise the core hyperinflammatory signature seen in severely ill COVID-19 patients." (PMID 39963132, 2025). "The pro-inflammatory cytokine surge in COVID-19, especially IL-6 and TNF-α, may further contribute to tissue damage and ulcer formation." (PMID 40546542, 2025). "A study of 1953 patients with COVID-19 showed elevated levels of IL-6, IL-8, TNF-α and IL-1B." (PMID 40236655, 2025). "This revealed higher plasma TNF-α protein in samples taken at the time of severe/critical COVID-19." (PMID 40532694, 2025). "TNF α is a biomarker for the severity and prognosis of COVID-19." (PMID 40300201, 2025). "Although both IL 8 and TNF α have been previously reported as associated with COVID-19 and identified by our primary MR as increasing the risk of more severe COVID-19, our replication analysis fails to further support their causal role." (PMID 41359762, 2025). "Other studies report higher levels of TNF-α in patients with severe or critical COVID-19." (PMID 40508859, 2025). "IMV was mainly required in COVID-19 patients with high TNF levels (TNFHIFNγH and TNFHIFNγN-L)." (PMID 39940907, 2025). "Elevated serum IL-6 and TNF-α are known predictors of severe COVID-19 and death." (PMID 41329757, 2025).